STAT3 (signal transducer and activator of transcription 3)
Diseases named in the same sentence as STAT3 in open-access papers (continued):
Sharing a sentence is not in itself a finding about the gene and the disease.
colitis (continued). "Recent circumstantial evidence has further strengthened the idea that the IL-6/gp130/STAT-3 signaling axis serves as both an autocrine and paracrine amplification loop in lung adenocarcinoma, multiple myeloma, Ras-transformed cancer cells, and a colitis-associated cancer model." (PMID 22022583, 2011). "Elevated STAT3 phosphorylation has been observed in both ulcerative colitis patients and specific animal colitis models." (PMID 40005956, 2025). "Disruption of IL‐6‐mediated STAT3 activation has been shown to attenuate colitis severity in animal models, highlighting the central role of IL‐6/STAT3 signaling in UC progression." (PMID 40387460, 2025). "To investigate the therapeutic mechanism of SPS in colitis, we examined the phosphorylation status of the STAT3/NF-κB signaling pathway." (PMID 41008172, 2025). "In rats with 2, 4, 6-trinitrobenzene sulfonic acid (TNBS)-induced colitis, CP reduced the expression of proinflammatory cytokines and blocked the phosphorylation of STAT3 and JAK2, resulting in significant relief of colitis." (PMID 40078988, 2025). "To improve their treatment options, we determined if targeting STAT3 with TTI-101, a small-molecule STAT3 inhibitor, was beneficial in the azoxymethane (AOM)-disodium sulfate (DSS) mouse model of colitis-associated CRC." (PMID 41226842, 2025). "The combined administration of mesalamine and PTX produced the most pronounced effect, significantly reducing IL‐6 and STAT3 levels by 57.93% (F = 505.4, p < 0.0001) and 68.91% (F = 153.3, p < 0.0001), respectively, in comparison to the colitis group." (PMID 40387460, 2025). "Oleanolic acid can directly bind to SHP2, and inhibit STAT3 phosphorylation and Th17 differentiation, thereby alleviating inflammatory responses and mitigating experimental colitis induced by TNBS in mice." (PMID 41008172, 2025). "Experiment in vivo confirmed that EGFR signaling in myeloid cells represents the main player of colitis-associated colorectal cancer (CAC), by activation of STAT3 and survivin genes in intestinal tumor cells." (PMID 39966897, 2025). "During progression of colitis, IL6/GP130/STAT3(Signal Transducer and Activator of Transcription 3) signaling pathway is upregulated in colonic epithelium, promoting development of colitis." (PMID 39821173, 2025). "The gut epithelial–specific depletion of C/EBPβ or STAT3 abolishes the protective role of TH17 cytokines against colitis progression." (PMID 40749055, 2025). "Treatment with mesalamine resulted in a modest but significant reduction in IL‐6 and STAT3 content by 12.71% (F = 505.4, p = 0.006) and 53.57% (F = 153.3, p = 0.004), respectively, relative to the colitis group." (PMID 40387460, 2025). "In a DSS-induced colitis mouse model, oral administration of Roseburia-derived extracellular vesicles improved colitis by downregulating NF-κB and STAT3 in colonic tissues." (PMID 41451329, 2025). "In a DSS-induced colitis model, the hyperactivation of Stat3 in myeloid cells in gp130757F/F mice ameliorated intestinal inflammation, which was attributed to the expansion and activation of MDSCs." (PMID 40244120, 2025). "The colitis group demonstrated a significant increase in colon IL‐6 and STAT3 levels by 6.77‐fold (F = 505.4, p < 0.0001) and 4.38‐fold (F = 153.3, p < 0.0001), respectively, compared to the normal control group." (PMID 40387460, 2025). "SIRT1, which is closely associated with cellular metabolism and stress responses, also interacts with the STAT3 pathway, modulating the inflammatory process in colitis." (PMID 40672369, 2025). "In conclusion, CHI3L1 serves as a key molecule linking epithelial inflammation to macrophage polarization, and its mechanism of regulating the immune microenvironment through the STAT3/NF-κB pathway provides a novel therapeutic target for colitis." (PMID 41008172, 2025). "Circadian disruption in gut epithelium reduces SCFA levels, leading to impaired barrier function, STAT3-driven inflammation, and worsened colitis." (PMID 41425940, 2025).
colitis (continued). "Wedelolactone markedly reduced the IL-1β-induced expression of COX-2, iNOS, TNF-α, and IL-6 in human chondrocytes by inhibiting NF-κB activation and further attenuated colonic inflammation in DSS-induced colitis via suppression of the IL-6/STAT3 axis." (PMID 41304898, 2025). "The IL-6/STAT3 signaling pathway is known to be involved in the pathogenesis of colitis and related cancers." (PMID 40295196, 2025). "While STING is recognized for epithelial repair in colitis via STAT3-dependent restitution colitis, its proinflammatory role in CE underscores tissue-specific signaling outcomes." (PMID 41583494, 2025). "This study demonstrated that SPS likely alleviates TNBS-induced colitis inflammation by suppressing the STAT3/NF-κB signaling pathway, thereby reducing M1 macrophage polarization." (PMID 41008172, 2025). "In colitis-associated tumorigenesis and human CRC cohorts, heightened IL-11 signaling tracks with worse outcomes and promotes tumor cell survival by engaging STAT3—a pathway that drives target genes relevant to CRC biology, including SOCS3 and surviving." (PMID 41153383, 2025). "Combining the STAT3 inhibitor JSI-124 with a strategy to inhibit IL-6-mediated production of the G-MDSC exosome miR-93-5p facilitates the prevention and treatment of colitis-associated cancer." (PMID 39990210, 2025). "High indole-3-lactic acid (ILA) production is a key tryptophan metabolic characteristic of L. plantarum which activated AHR downstream signaling (such as CYP1A1, IL-22, and STAT3) to alleviate colitis." (PMID 41019044, 2025). "This palmitoylation cycle of STAT3 is thought to play a notable role in the initiation and progression of colitis." (PMID 38233383, 2024). "In fact, they suggest that Lactobacillus reuteri induced LPLs to secrete IL-22 through AhR and then activated STAT3 phosphorylation to counteract epithelial damage in DSS-induced colitis mice." (PMID 39517263, 2024). "We observe similar hepatic functions of Rela and Stat3 that amplify the immune response during experimental colitis, aggravating intestinal pathologies." (PMID 39137024, 2024). "Similar outcomes indicated the ability of GAL to abate the expression of JAK/STAT3 in a model of colitis, high-fat diet, and AKI while improving SOCS3 expression in inflammatory bowel disease." (PMID 37429998, 2024). "Statistical graphs delineated that the ratios of phospho-JAK2/JAK and phospho-STAT3/STAT3 were lower in the UTI group than those in the colitis group." (PMID 38397811, 2024). "This process is known as the palmitoylation cycle of STAT3 and has been shown to enhance Th17 differentiation and exacerbate colitis." (PMID 38233383, 2024). "Our experimental findings confirmed a 2.272 ± .167‐fold increase in STAT3 mRNA in DSS‐induced colitis mice." (PMID 38533646, 2024). "Both in vivo and in vitro experimental results demonstrate that CSCC alleviates DSS-induced colitis in mice by regulating STAT3 activation through Gpr43." (PMID 39329121, 2024). "This increment, along with the earlier results, suggests that HSPA9 downregulation possibly exacerbates colitis by enhancing infiltration and triggering macrophage activation via the STAT3 pathway." (PMID 38467701, 2024). "Recent research has increasingly links the signal transducer and activator of transcription-3 (STAT3) pathway to IBD, with the IL-6/STAT3 signaling pathway consistently recognized as a noteworthy factor in colitis development." (PMID 38233383, 2024). "In summary, dietary LCFAs, especially PA, can enter cells through CD36 uptake and participate in the palmitoylation cycle of STAT3, leading to the disruption of the intestinal barrier and exacerbation of colitis." (PMID 38233383, 2024). "The activation of the IL-6/STAT3 pathway has consistently been identified as a substantial component in colitis." (PMID 38233383, 2024). "Towards this, our work demonstrates the pro-inflammatory potential of CDCA during colitis following the activation of the Rela/Stat3 pathway." (PMID 39137024, 2024).
colitis (continued). "We further define a colitis resistance model based on the liver-specific knockout animals and propose a Rela/Stat3-CYP enzyme-mediated elevation of primary bile acid leading to immune-mediated damage to the gut." (PMID 39137024, 2024). "Numerous studies have shown that JAK2/STAT3 pathway is an important pathway inflammation influence colitis." (PMID 38626146, 2024). "Collectively, our results provide evidence that dietary LCFAs exacerbate colitis by regulating STAT3 palmitoylation through CD36-mediated endocytosis." (PMID 38233383, 2024). "Mice with AOM/DSS colitis exhibited significantly elevated levels of proteins associated with cell death, including PCNA, PTEN, VEGF, COX-2, and STAT-3." (PMID 39598375, 2024). "Previous research revealed that BTW alleviates experimental colitis by suppressing the IL-6/STAT3 signaling pathway, modulating the Th17/Treg cell balance, and improving microflora structure and bile acid metabolisms." (PMID 38974042, 2024). "Inhibition of JAK2 or STAT3 activity has been shown to ameliorate colitis severity and promote mucosal healing in preclinical models of IBD." (PMID 39187810, 2024). "In this study, inflammasome-associated factors, including p-STAT3, NLRP3, IL-1β, and caspase-1, were significantly enhanced in a DSS-induced mouse colitis model." (PMID 39329121, 2024). "Collectively, these results highlight that LCFAs aggravate colitis by enhancing STAT3 phosphorylation and its translocation into the nucleus." (PMID 38233383, 2024). "In the pathogenesis of colitis, IL-6 and IL-22 are inflammation-associated markers that correlate with the activation of the JAK and STAT3 pathways." (PMID 39133435, 2024). "Our research also confirms that XYKJP inhibits IL-6 expression and phosphorylation of JAK2 and STAT3, thereby reducing the inflammatory response to colitis." (PMID 39133435, 2024). "IL-6/JAK2/STAT3 signaling is a vital axis involved in cell homeostasis and inflammatory signal amplification in various diseases, such as colitis." (PMID 39133435, 2024). "Unlike ATCC BAA-835 or Am06, Am03 did not counteract the decrease in crypt Ki67-positive cells and p-STAT3 induced by colitis." (PMID 39734222, 2024). "In the subsequent phase of our investigation, we focused on the role of STAT3 signaling in exacerbating experimental colitis due to LCFA exposure." (PMID 38233383, 2024). "Studies on colitis suggest that activation of STAT3 signaling stimulated by IL-22 confers protective effects on the colonic mucosal immune system." (PMID 38732497, 2024). "In experimental colitis models, histone deacetylase (HDAC) suppressed Th17 differentiation through the IL-6/STAT3/IL-17 pathway, thereby alleviating experimental colitis." (PMID 39020448, 2024). "It was also reported that berberine effectively inhibits the activation of the IL-6/STAT3/NF-κB pathway in models of DSS-induced colitis, offering a potential treatment for ulcerative colitis." (PMID 38998031, 2024). "In a previous study using an animal model of colitis, it was discovered that curcumin treatment drastically reduced STAT3 dimer DNA-binding activity and phospho-STAT3 activity." (PMID 38751599, 2024). "Here, we identify a novel hepatic gene program regulated by Rela and Stat3 that accentuates the inflammation in an acute experimental colitis model." (PMID 39137024, 2024). "In contrast, STAT3 activation in CD4+ T cells leads to the prevention of apoptosis of pathogenic CD4+ T cells with the ensuing manifestation of chronic intestinal inflammation, suggesting that STAT3 activation in CD4+ T cells promotes colitis." (PMID 37296943, 2023). "The protective effect of nicotine against DSS-induced colitis was induced by expression of miR-124 and downstream inhibition of STAT3, indicating the potential role of miR-124/STAT3 as a key player in the therapeutic armamentarium of UC." (PMID 36768556, 2023).
colitis (continued). "RNA-seq revealed an overall increase in the expression of the STAT family of B cells during colitis, and the STAT3 expression was most consistent with that of IL-35." (PMID 36797242, 2023). "Human catestatin also regulates intestinal inflammation via the macrophage population and through a STAT-3 dependent pathway in a murine model of colitis." (PMID 36675038, 2023). "In a dose-dependent manner, gallic acid was shown to inhibit DSS-induced colitis in mice through the inhibition of STAT3 phosphorylation." (PMID 36765950, 2023). "Strikingly, the use of C188-9, a small molecule targeting STAT3, mitigates colitis in a murine immunodeficiency model receiving eEF2K knockout (KO) CD4+ T cells." (PMID 37875468, 2023). "The expression of signal transducer and activator of transcription 3 (STAT3) phosphorylation in colonic mucosa was detected in B. fragilis-treated mice in colitis." (PMID 37114045, 2023). "We used the dextran sodium sulfate (DSS) murine model of colitis, which is widely used in preclinical studies, to determine the contribution of STAT3 to IBD." (PMID 37296943, 2023). "The results of our studies examining the impact of modulating STAT3 activity, genetically or pharmacologically, in all three cell compartments suggest a dominant role for STAT3 within the T cell compartment in the pathogenesis of DSS-induced colitis." (PMID 37296943, 2023). "Correspondingly, a probiotic Lactobacillus motivates STAT3 signaling to promote stem cell proliferation in DSS-induced colitis." (PMID 37114045, 2023). "Exacerbation of colitis is achieved through the inhibition of NF-κB/STAT3 signaling, and the activation of HO-1/Nrf2/SIRT1 pathways." (PMID 37359553, 2023). "In the current studies, we used the dextran sodium sulfate (DSS) murine model of colitis, which is widely used in preclinical studies, to determine the contribution of STAT3 to IBD." (PMID 37296943, 2023). "Following colitis induction, the protein expressions of p-p65 and p-STAT3, active forms of p65 and STAT3, were significantly upregulated." (PMID 37153794, 2023). "Pro-Nifuroxazide was first used as an antibiotic agent for diarrhea or colitis which reduces kinase phosphorylation in the bone marrow, resulting in the downregulation of the signal transducer and activator of transcription 3 (STAT-3) target gene mcl-1." (PMID 37143168, 2023). "Conditional knockout mice with a specific STAT3 or ATG16L1 deficiency in IECs can affect the secretion of IL-22, which is associated with wound healing and has a high risk of developing colitis." (PMID 37875976, 2023). "It has been reported that naringin inhibits MDSCs, proinflammatory mediators (GM-CSF/M-CSF, IL-6, TNF-ɑ), and the NF-κB/IL-6/STAT3 cascade in colorectal tissue, reducing the severity of colitis and colorectal adenoma." (PMID 36593497, 2023). "Studies from animal models, including the DSS-induced colitis model, have established that STAT3 activation promotes pathogenesis of UC and carcinogenesis." (PMID 37283760, 2023). "In the current study, we determined the contribution of STAT3 to IBD across all tissues by examining DSS-induced colitis in mice that express only STAT3α and in mice treated with TTI-101, a direct small-molecule inhibitor of both isoforms of STAT3." (PMID 37296943, 2023). "In an experimental colitis model, the administration of a mixture of heat-inactivated probiotics downregulated IL-6, IL-23, STAT3, and p-STAT3 expression in colonic tissues of colitic rats." (PMID 37894114, 2023). "A previous study has revealed that the motivation of STAT3 signaling promotes colonic mucus secretion in DSS-induced colitis in mice." (PMID 37114045, 2023). "FGF21 deletion protected mice from DSS-induced acute colitis by increasing IL-22 expression-mediated epithelial STAT3 activation, which decreased intestinal inflammation and maintained intestinal goblet cell and Paneth cell homeostasis." (PMID 37432218, 2023).
colitis (continued). "Targeting inhibition of NF-κB and STAT3 has become an important strategy for the treatment of CD-like experimental colitis." (PMID 37153794, 2023). "We also found that NFκB signaling components were elevated in the model mice, as well as the protein expression of JAK2, p-Stat3/Stat3, and IL-6, suggesting increased colitis in the model group." (PMID 38004214, 2023). "Using a T-cell transfer model of colitis, other studies have shown that STAT3 within T cells is essential for driving colitis via the induction of Th17 cell responses." (PMID 37296943, 2023). "Significantly, CD73-ERCs regulate DC maturation and activation via the STAT3 pathway, regulate innate immune responses, and exert efficient therapeutic efficacy against colitis." (PMID 37180168, 2023). "M10, a novel derivative of Myricetin, prevents ER stress-induced autophagy in inflamed colonic mucosal cells by targeting the NF-κB/IL-6/STAT3 pathway, which develops M10 as a promising regimen in the chemoprevention of colitis and colorectal cancer." (PMID 36593497, 2023). "Numerous studies have demonstrated that epithelial STAT3 is essential for maintaining gut barrier integrity, whereas S1P promotes the activation of STAT3, thus contributing to the development of colitis-related cancers." (PMID 36985809, 2023). "Long non-coding RNA (lncRNA) FAM64A promotes Th17 differentiation and colitis-related tumor formation by positively regulating STAT3 activity." (PMID 37964307, 2023). "STAT3 plays a critical role in colitis pathology, and its activation is mediated by multiple cytokines such as IL-6." (PMID 37432218, 2023). "It has been demonstrated in recent research that oral treatment of L. acidophilus efficiently reduced the production of IL‐17, TNF‐α, and IL‐23, as well as STAT3 and phosphorylated STAT3, in the colon tissue of a colitis model created by DSS." (PMID 37904683, 2023). "As such, further study is required to elucidate the role of the STAT3/SOCS3 axis in myeloid cells to understand their role in the pathogenesis of colitis." (PMID 37283760, 2023). "A previous study has revealed a link between IL-22 and STAT3 signaling in intestinal epithelial renewal in DSS-induced colitis." (PMID 37114045, 2023). "Previous studies showed higher activation of NF-κB, ERK, and STAT3 in the colon of Nlrp12–/– mice during acute DSS-induced colitis." (PMID 37581937, 2023). "In the CE100+SA group, we observed a normalization of the concentration of both total and phosphorylated STAT3 (p < 0.001 in both cases), yielding a lower p-STAT3/STAT3 ratio than in the colitis group (p < 0.05)." (PMID 37049797, 2023). "The findings showed that XJS ameliorated TNBS-induced experimental colitis via suppression of ferroptosis positively regulated by the FGL1/NF-κB/STAT3 positive feedback loop." (PMID 37153794, 2023). "An activated IL‐6R/STAT3/miR‐34a feedback loop was required and essential for maintaining the mesenchymal phenotype of CRC and colitis‐associated intestinal tumours." (PMID 37138536, 2023). "STAT3 in three cell lineages—myeloid cells, enterocytes, and T cells—has been found to contribute to colitis in mice and humans, but in contrasting ways." (PMID 37296943, 2023). "Some upstream regulators, including TNFR2, IL1R1, IKKα, IKKβ and GP130, were all targets of miR‐148a, which led to the activation of NF‐κB and STAT3 pathways and increase of colitis." (PMID 37138536, 2023). "STAT3 plays a crucial role in maintaining intestinal homeostasis and strongly protects against chemically induced colitis." (PMID 37875976, 2023). "We examined the contribution of STAT3 across all cell compartments in the dextran sodium sulfate (DSS) model of colitis by modulating levels of STAT3 activity both genetically and pharmacologically." (PMID 37296943, 2023). "Previously, research in a colitis animal model reported that the phospho-STAT3 activity and DNA-binding activity of STAT3 dimers were significantly decreased following therapy with curcumin." (PMID 36297027, 2022).